VDR (vitamin D receptor)
Diseases named in the same sentence as VDR in open-access papers (continued):
Sharing a sentence is not in itself a finding about the gene and the disease.
cancer (continued). "Moreover, upon binding of its ligand VitD and nuclear translocation, VDR is also able to form heterodimers with the retinoid X receptor (RXR), thereby activating various cancer-relevant transcriptional programs." (PMID 36902107, 2023). "ESS2 regulates cancer progression, PPAR-γ and VDR responses, and EMT signaling in PC3 cells." (PMID 37524814, 2023). "Furthermore, it would be interesting to analyse the expression of CYP27B1 and its interactions with VDR and CYP24A1 in cancer cells." (PMID 36362766, 2022). "Furthermore, VDR participates in large protein complexes with chromatin modifiers, such as KDM6B and BRD7, to provoke epigenetic alterations in cancer cells." (PMID 35406562, 2022). "Moreover, CD11A, ZNF278, VDR, ZIC3, and NFκB also play critical roles in the modulation of oncogenic processes in many type cancers." (PMID 35456435, 2022). "Moreover, an analysis of the VDR and CYP24A1 expression of circulating disseminated cancer cells and the corresponding primary cancer tissues would have been interesting for studying the metastatic process more precisely." (PMID 36362766, 2022). "VDR is involved in the induction of p27(Kip1) by VD3 and may interact with Sp1 to modulate the expression of target genes in LNCaP cancer cells." (PMID 35734414, 2022). "Thus, stratification of patient cohorts according to combined VitD level–VDR expression profiles will certainly reveal a more realistic picture of how these variables indeed influence the prognosis and survival of HNSCC and cancer patients in general." (PMID 36291915, 2022). "Other studies and meta-analyses sustained contradictory data, indicating that vitamin D3 does not predict cancer survival rate and that VDR expression is variable in tumors." (PMID 36101414, 2022). "Taken together, these results suggest a role of VitD/VDR in HNSCC metastasis as well, and that VitD treatments may prevent cancer from spreading (at least) by affecting E-cadherin-regulated EMT." (PMID 36291915, 2022). "Thus VDR, which is expressed at a systemic level, may act as a negative tumor suppressor regulator in physiological conditions and could be impaired in cancer patients, thereby promoting cancer transformation and other cancer-related sequelae, including bone health impairment." (PMID 36012901, 2022). "In general, the response of cancer cell lines to 1,25-OH-D is varied and dependent on their specific genome alterations, not on the VDR itself." (PMID 34638264, 2021). "Numerous studies have investigated the potential benefit of VD-induced differentiation through interaction with VDR in different cancers including AML, without encouraging results." (PMID 34680392, 2021). "Interestingly, they demonstrated that miR-372/373 overexpression leads to reduced expression of VDR RNA and protein in CRC cells, which contributes to the maintenance of the cancer stem cell phenotype." (PMID 33227961, 2020). "In specific cancer cells that did not express VDR, such as gastric cancer cells, 1α,25(OH)2VD3 induced apoptosis by upregulating the gene and protein expression of aSMase." (PMID 33126474, 2020). "To investigate the effects of VDR on the phenotypes of CRC stem cells, we first confirmed that VDR expression was lower in CRC stem cells than in non-stem cancer cells." (PMID 32900990, 2020). "In that study, it was also pointed out that the treatment of CAFs with calcitriol, an active type of Vitamin D, induces vitamin D receptor (VDR)-mediated signaling and remarkably downregulates miRNA-10a-5p levels in exosomes as well as exosome-receiving cancer cells." (PMID 32756339, 2020). "Significant difference on VDR expression could be obtained between the PTC tissues and the non‐cancer tissues." (PMID 32285621, 2020). "Both VDR and ZBTB20 were previously shown to operate as tumor suppressors in cancer." (PMID 32855526, 2020).
cancer (continued). "Since VDR was found on multiple subcellular locations in cancer cells, and there were no previous records in the literature about this, we concluded it best to evaluate the fraction of stained cancer cells at all sites." (PMID 31358030, 2019). "VDR (NR1I1) is the cellular receptor for 1,25-dihydroxyvitamin D (1,25[OH]2 vitamin D3), which has multiple regulatory effects on human metabolism, immunity, and cancer." (PMID 30804707, 2019). "In terms of MBD management, the proportions of phosphate binder use, intravenous vitamin D receptor activator use, and cinacalcet use did not markedly differ by cancer status." (PMID 30623084, 2018). "The vitamin D receptor (VDR) exerts its biological influence by binding with circulating vitamin D, and thereby contributes to the regulation of apoptosis and cell differentiation, and suppression of cancer cell proliferation." (PMID 30344947, 2018). "Ras-like small GTPase activity contained in RAB39A may contribute to cancer developments through RXR and VDR signaling." (PMID 29515775, 2018). "VDR expression has also been suggested to be up-regulated in early-stage cancer but not in advanced cancer." (PMID 30150667, 2018). "Most cancers express not only the VDR but also CYP27B1 and CYP24A1 thus allowing cancer cells to regulate locally 1,25(OH)2D levels, and it has been reported that cancers expressing CYP27B1 tend to be well differentiated while cancers which do not express CYP27B1 tend to be poorly differentiated." (PMID 29951549, 2018). "Another point is that vitamin D-induced VDR overexpression in the AH130 hosts does not worsen muscle wasting, in some way opposing to the potential involvement of VDR in causing cancer-induced muscle depletion." (PMID 28423519, 2017). "The presence of a high cytoplasmic VDR level was also observed in cancers with a smaller percentage of non-classic differentiations." (PMID 26501255, 2015). "Our results imply that an elevated level of VDR does not indicate a good prognosis because we observed higher levels of VDR in more invasive cancers." (PMID 26068789, 2015). "Our results of decreased VDR expression in OSCC compared with SIN lesions can be explained with the clonal selection model of carcinogenesis, which proposes that there is a subsequent clonal selection of cancer cells or putative CSC during carcinogenesis." (PMID 25662556, 2015). "In organ culture models, VDR agonists such as 25(OH)D3 and 1α,25(OH)2D3 reduce the incidence of DMBA induced pre-neoplastic lesions suggesting direct anti-cancer effects of these metabolites on mammary tissue." (PMID 24982636, 2014). "In further analyses stratified by ER status, one SNP in VDR and seven SNPs in CYP24A1 were specifically associated with ER- but not ER+ cancer risk, and the associations differed between AA and EA women." (PMID 22480149, 2012). "Although in vivo and in vitro laboratory studies provide strong evidence in supporting that vitamin D via VDR possesses antiprostate cancer activities, epidemiological studies have not shown consistent results for vitamin D's antiprostate cancer activities." (PMID 21991434, 2011). "Notably, overexpression of VDR in CD133+ cells suppressed Wnt/β-catenin signaling and led to the formation of smaller, less viable spheroids, suggesting that VD may reduce cancer stemness and enhance tamoxifen sensitivity." (PMID 41374952, 2025). "Non-calcaemic agonists of the vitamin D receptor (VDR) could be better candidates for cancer treatment." (PMID 39796220, 2025). "Finally, because we did not generate new VDR ChIP-seq data, we had to rely upon other published VDR binding site data from undifferentiated colonoids or human cancer cell lines (LS180, RWPE1)." (PMID 40535337, 2025). "However, the negative correlation between cytoplasmic VDR expression and tumor progression in some cancer types suggests VDR as a potential target of downregulation or ablation." (PMID 38265102, 2024).
cancer (continued). "Furthermore, many studies have demonstrated the role of 1,25-(OH)2D3 in regulating VDR and various other genes such as TNF-α, CYP3A4, c-FOS, c-Jun, CCND1, Snail1, Snail2, CDH1, AXIN2, TCF-4, TCF7L2, etc. to exhibit anti-cancer property by suppressing the CRC hallmarks." (PMID 38372868, 2024). "The consistency with which VDR is upregulated in response to inhibition of miR-10b regardless of species, cancer type, or method and its status as a predicted target of miR-10b makes the gene particularly interesting for future studies in miR-10b-based therapies." (PMID 39189967, 2024). "Moreover, given the observed decline in the expression of CYP27B1, VDR, CYP11A1, and RORα/γ during cancer progression, as previously discussed, the utility of VD-based treatments may be confined to early rather than advanced stages of the disease." (PMID 38689243, 2024). "We analyzed the relationships between VDR expression and immune infiltration levels of NK cells, CD4+ T cells, CD8+ T cells, Tregs, B cells, cancer-related fibroblasts, macrophages, neutrophils, myeloid dendritic cells, and monocytes in various cancer types in TCGA database." (PMID 38639057, 2024). "Therefore, understanding the prognostic and immunological implications of the VDR in CESC is crucial because it could potentially lead to the development of novel treatments and therapies for this type of cancer." (PMID 39268267, 2024). "We found that VDR expression was significantly downregulated in CESC compared to normal tissues, which could encourage the potential use of VDR as a prognostic biomarker in this cancer." (PMID 39268267, 2024). "Interestingly, VDR has been found to be elevated in many cancer cells, while a lack of vit-D3 was reported to be associated with the increased potential to develop cancers." (PMID 37835527, 2023). "Additionally, our findings are in line with a 2016 systematic review of GxE in all cancer, which identified XRCC1 and VDR as two of the most frequently reported genes with interactions and sun exposure as one of the most commonly reported environmental exposures." (PMID 37537768, 2023). "To independently confirm the relevance of VDR expression in the HNC patients, we bioinformatically analyzed the PANCAN dataset acquired from The Cancer Genome Atlas (TCGA), encompassing more than 12,000 samples of cancer patients of various entities and clinical backgrounds." (PMID 36902107, 2023). "Thus, there is good evidence that vitamin D3 is anti‐inflammatory which would be expected to be beneficial in all stages of cancer and irrespective of tumour VDR signalling." (PMID 35445563, 2022). "We first investigated VDR expression patterns and their correlation with clinical parameters in the PANCAN data set obtained from The Cancer Genome Atlas (TCGA), comprising more than 12,000 samples of cancer patients of various entities and clinical backgrounds." (PMID 36291915, 2022). "Thus, although cancer cells (e.g., murine cancer cell lines) are not sensitive to the antiproliferative activity of vitamin D3 in vitro (despite the presence of the vitamin D receptor, VDR), they show significant sensitivity to vitamin D derivatives in vivo." (PMID 36230508, 2022). "However, there was a non-significant trend in high-grade cancers towards low nuclear VDR expressions in bone metastases." (PMID 36362766, 2022). "Two important considerations in the study of the action of 1,25-(OH)2D3 and analogues in experimental cancer systems are the expression of vitamin D receptor (VDR), which is frequently low or absent, and the high doses of its ligands that are usually required to observe effects." (PMID 35406059, 2022). "However, the detailed mechanism of such ligand-independent VDR-mediated gene activation in HNSCC and cancer cell in general, and how it might be involved in the development of resistances, must be dissected in further studies." (PMID 36291915, 2022).
cancer (continued). "With the exception of three clusters of NRs representing NR classes I (cluster I: RORC, VDR, PPARA, NR1D1, THRA, RORA, NR1H3; cluster II: RARB, PPARG, THRB) and III (cluster III: ESR1, PGR, AR, ESRRG), NR class was not a good determinate of NR expression patterns in the different cancer types." (PMID 32024906, 2020). "They later showed that these receptors were present in many, but not in all, cancer cell lines and tissues, thus concluding that the VDR was not a marker for malignancy but might play a role in the pathogenesis or evolution of cancer." (PMID 30321335, 2019). "Additionally, because the expression levels of CYP27B1, VDR, CYP11A1, and RORα/γ in cancer cells progressively decline during cancer progression the effectiveness of vitamin D-based therapy may be limited to only early stages, but not late stages, of cancer." (PMID 29657326, 2018). "This suggests that the overexpression of CYP24A1 in many cancer cells may not be the result of normal physiological processes regulated by calcitriol–VDR-dependent mechanisms." (PMID 29657326, 2018). "The observation that VDR is overexpressed in the skeletal muscle of tumor-bearing animals suggests that the VitD/VDR-dependent signaling pathway might contribute to cancer-induced muscle wasting, despite the lack of effect of VitD supplementation." (PMID 28423519, 2017). "Thus, VDR overexpression in these cells upregulates E-cadherin, downregulates SNAIL1, TWIST1, and MMP9, and reduces cell ability to form mammospheres, an attribute of breast normal and cancer stem cells." (PMID 26880977, 2016). "However, a combined lack of nuclear and cytoplasmic VDR was seen in nine of 71 cancer patients (12.7%)." (PMID 26501255, 2015). "Accordingly, treatment of HaCaT cells with vitamin D downregulated both subunits, suggesting that VDR may inhibit the respiratory chain and redirect TCA intermediates toward biosynthesis, thus contributing to the metabolic switch that is typical of cancer cells." (PMID 25546457, 2014). "The vitamin D receptor (VDR) is involved in multiple pathways such as insulin-like growth factor (IGF) signaling; it also has a role in the inflammation and estrogen-related pathways that may be related to the prognosis of cancer." (PMID 23691496, 2013). "In addition, the anti-cancer and anti-inflammatory effects of vitamin D are regulated through gene transcription via the vitamin D receptor (VDR) and through non-genomic signaling cascades." (PMID 24216707, 2013). "Additionally, it has been shown that the expression of mRNA for CYP27B1 and the VDR was higher in carcinomas versus non-neoplastic tissue." (PMID 20831823, 2010). "Thus, light has not been adequately shed on the functional role of VDR signaling in cancers." (PMID 38318147, 2024). "Although it has been shown that vitamin D can inhibit the development of cancer even in cell lines or tissues that express a mutant version of the VDR, additional investigations are needed to determine whether or not VDR expression is a prerequisite for vitamin D to have anticancer activity." (PMID 39335182, 2024). "Moreover, the VDR activation due to high vitamin D concentration may induce the expression of CYP3A, a cytochrome P450 enzyme that has been proved to detoxify LCA in the liver and intestine, contrasting its proliferative effects on cancer cells." (PMID 37887360, 2023). "Regarding the question of whether 25(OH)D concentrations above 30 ng/mL might be a marker of a healthy lifestyle rather than causative for moderate health benefits, it should be emphasized that anti-cancer effects resulted from calcitriol-activated VDR but not from the overall 25(OH)D in plasma." (PMID 36364774, 2022). "However, only one of these studies was performed on a cancer cell line delivered from the colon, which might not have been the most suitable model for VDR genome occupancy in IBD." (PMID 36233580, 2022).
cancer (continued). "The main role of 1,25D3, bound to its receptor, the transcription factor vitamin D receptor (VDR), is the regulation of serum calcium and phosphorus homeostasis, but it also regulates the expression of many genes that might play a role in the development of cancer." (PMID 36145244, 2022). "Moreover, the overexpression of CYP24A1 in numerous cancer cells may not be a result of normal physiological processes mediated by calcitriol–VDR-dependent mechanisms." (PMID 34208589, 2021). "On the whole, these observations suggest that: i) a direct link between VitD plasma levels and the outcome of cancer cachexia is lacking; and ii) a ligand-independent dysregulation of VDR signaling pathway could be involved in the pathogenesis of cancer-induced muscle wasting." (PMID 28423519, 2017). "Our study showed the VDR Trs2107301Trs2228570Crs1989969Grs11568820 haplotype was associated with a significantly reduced risk of GCA, which indicated that polymorphism in single locus might not significantly modify the risk of cancer." (PMID 28489590, 2017). "However, certain cancer cell lines do not express VDR and are unresponsive to 1,25(OH)2D3." (PMID 26880977, 2016). "However, it could not be excluded that these differences in VDR protein level were affected by histological origin of cancer cells." (PMID 26501255, 2015). "However, the extraordinarily high level of CYP24A1 activity in highly malignant cancers probably does not result from up-regulation by the 1,25-(OH)2D3/VDR system but may be due to overexpression of the gene." (PMID 24213465, 2012). "Surprisingly, when MCF-7 stem cells were sorted using a CD133 fluorescent antibody, VDR resulted overexpressed, compared to non-stem MCF-7 cancer cells (CD133-) used as control." (PMID 32560347, 2020). "Novel literature demonstrates that, besides the well-established NR, other receptors, including the retinoid X receptor (RXR), thyroid hormone receptors (THRs) and vitamin D receptor (VDR), play a significant role in the pathophysiology not only of BC but also of other cancer entities." (PMID 34359656, 2021). "It is reasonable to propose that there may also exist under-appreciated genomic functions for other type II nuclear receptors (e.g., VDR, PPARs, FXR, LXRs, CAR) that exert genomic functions in the absence of exogenous ligand and are potential targets in cancer." (PMID 30120411, 2019). "Although CYP24A1 expression is induced by calcitriol–VDR activation via negative feedback regulation, the high level of CYP24A1 expression observed in cancer cells is unlikely to be mediated by VDR activation because VDR expression and activity are downregulated in most cancer." (PMID 29657326, 2018).